SLC22A2 (solute carrier family 22 member 2)
Description:
Electrogenic voltage-dependent uniporter that mediates the transport of a variety of organic cations such as endogenous bioactive amines, cationic drugs and xenobiotics. Functions as a Na(+)-independent, bidirectional uniporter. Cation cellular uptake or release is driven by the electrochemical potential, i.e. membrane potential and concentration gradient. However, may also engage electroneutral cation exchange when saturating concentrations of cation substrates are reached (By similarity). Predominantly expressed at the basolateral membrane of hepatocytes and proximal tubules and involved in the uptake and disposition of cationic compounds by hepatic and renal clearance from the blood flow. Implicated in monoamine neurotransmitters uptake such as histamine, dopamine, adrenaline/epinephrine, noradrenaline/norepinephrine, serotonin and tyramine, thereby supporting a physiological role in the central nervous system by regulating interstitial concentrations of neurotransmitters. Also capable of transporting dopaminergic neuromodulators cyclo(his-pro), salsolinol and N-methyl-salsolinol, thereby involved in the maintenance of dopaminergic cell integrity in the central nervous system. Mediates the bidirectional transport of acetylcholine (ACh) at the apical membrane of ciliated cell in airway epithelium, thereby playing a role in luminal release of ACh from bronchial epithelium. Also transports guanidine and endogenous monoamines such as vitamin B1/thiamine, creatinine and N-1-methylnicotinamide (NMN). Mediates the uptake and efflux of choline. Mediates the bidirectional transport of polyamine agmatine and the uptake of polyamines putrescine and spermidine. Able to transport non-amine endogenous compounds such as prostaglandin E2 (PGE2) and prostaglandin F2-alpha (PGF2-alpha). Also involved in the uptake of xenobiotic 4-(4-(dimethylamino)styryl)-N-methylpyridinium (ASP). May contribute to regulate the transport of organic compounds in testis across the blood-testis-barrier (Probable). [Isoform 2]: In contrast with isoform 1, not able to transport guanidine, creatinine, cimetidine and metformin.
Synonyms: OCT2
Tractability: Small molecule: a structure with a bound ligand is known; a high-quality ligand is known; it belongs to a druggable protein family. Antibody: UniProt places it where antibodies can reach, with high confidence; its Gene Ontology location is reachable by antibodies, with high confidence; UniProt predicts a signal peptide or a membrane-spanning region. PROTAC: a small molecule that binds it is known.
Target class: SLC superfamily of solute carriers; Electrochemical transporter; SLC22 family of organic cation and anion transporters; Transporter
Safety:
Unwanted effects reported when the protein is acted on. In parentheses: how it was acted on, where the effect was seen, and who reports it.
cardiotoxicity (source: ClinPGx)
cisplatin-induced ototoxicity (source: ClinPGx)
hepatotoxicity (source: ClinPGx)
nephrotoxicity (source: ClinPGx)
toxicity, specifically hepatotoxicity (source: ClinPGx)
Gene: Protein-coding gene on chromosome 6 (160,171,061 to 160,277,638, reverse strand). Ensembl gene ENSG00000112499.
Subcellular location: Basolateral cell membrane; Basal cell membrane; Apical cell membrane
Pathways (Reactome):
Neuronal System: Neurotransmitter clearance; Norepinephrine Neurotransmitter Release Cycle
Transport of small molecules: SLC-mediated transport of neurotransmitters; SLC-mediated transport of organic cations
Drug ADME: Abacavir transmembrane transport
Gene Ontology:
Molecular function: acetylcholine transmembrane transporter activity; amine transmembrane transporter activity; choline transmembrane transporter activity; efflux transmembrane transporter activity; L-amino acid transmembrane transporter activity; L-arginine transmembrane transporter activity; monoamine transmembrane transporter activity; neurotransmitter transmembrane transporter activity; prostaglandin transmembrane transporter activity; putrescine transmembrane transporter activity; pyrimidine nucleoside transmembrane transporter activity; quaternary ammonium group transmembrane transporter activity; thiamine transmembrane transporter activity; toxin transmembrane transporter activity; transmembrane transporter activity; xenobiotic transmembrane transporter activity; spermidine transmembrane transporter activity
Biological process: acetylcholine transport; amine transport; amino acid import across plasma membrane; cellular detoxification; choline transport; dopamine uptake; export across plasma membrane; histamine transport; histamine uptake; L-alpha-amino acid transmembrane transport; L-arginine import across plasma membrane; neurotransmitter transport; norepinephrine uptake; prostaglandin transport; putrescine transport; serotonin uptake; thiamine transmembrane transport; transmembrane transport; xenobiotic transport; purine-containing compound transmembrane transport; spermidine transport; transport across blood-brain barrier; quaternary ammonium group transport; spermidine transmembrane transport
Cellular component: apical plasma membrane; basal plasma membrane; extracellular exosome; plasma membrane; basolateral plasma membrane; membrane; presynapse
Genetic constraint (gnomAD): Loss-of-function variants: 26 observed, 32.29 expected, observed/expected ratio (o/e) 0.81, 90% interval 0.59 to 1.12. The upper end of that interval is the gene's LOEUF score, 1.12, which puts it in group 4 of 6, group 1 being the genes least tolerant of losing a copy. Missense variants: 479 observed, 495.02 expected, observed/expected ratio (o/e) 0.97, 90% interval 0.9 to 1.04. Synonymous variants: 215 observed, 194.66 expected, observed/expected ratio (o/e) 1.1, 90% interval 0.99 to 1.24.
Homologues: Orthologues: chimpanzee SLC22A2 (96% identical), macaque SLC22A2 (91% identical), dog SLC22A2 (85% identical), pig SLC22A2 (85% identical), mouse Slc22a2 (83% identical), rabbit SLC22A2 (82% identical), rat Slc22a2 (80% identical), guinea pig SLC22A2 (73% identical), tropical clawed frog slc22a2 (60% identical), zebrafish slc22a2 (50% identical), Drosophila melanogaster Orct (31% identical), Caenorhabditis elegans oct-1 (30% identical), and 38 more. Paralogues in human: SLC22A1 (70% identical), SLC22A3 (49% identical), SLC22A5 (32% identical), SLC22A4 (32% identical), SLC22A8 (31% identical), SLC22A6 (30% identical), SLC22A13 (30% identical), SLC22A11 (28% identical), SLC22A12 (27% identical), SLC22A15 (27% identical), SLC22A16 (27% identical), SLC22A7 (27% identical), and 10 more.
Diseases named in the same sentence as SLC22A2 in open-access papers:
SLC22A2 is named in the same sentence as 56 diseases in open-access papers, as found by Europe PMC text mining. Sharing a sentence is not in itself a finding about the gene and the disease. The quoted sentences say what the papers report.
diabetes (5 papers, 2016 to 2025). "The objective of this study was to investigate the relationship between twenty-one single nucleotide polymorphisms (SNPs) in the SLC22A1, SLC22A2, and SLC22A3 genes and their effects on metformin pharmacogenetics in Jordanian patients diagnosed with type 2 diabetes mellitus." (PMID 30934600, 2019). "Finally, after adjusting for BMI and age at diabetes diagnosis using multinomial logistic regression, this study found a genetic association between glycemic control and all tested SNPs within SLC22A1, SLC22A2 and SLC22A3 genes." (PMID 30934600, 2019).
renal cell carcinoma (5 papers, 2017 to 2024). "These 27 CTTs including 8 genes CTNNA1, PSMB6, PSMD12, SESN2, SLC22A2, UBE2J2, and NAE1 appeared in the SL pairs of renal cell carcinoma in previous literature studies." (PMID 38074121, 2023). "Before discussing the SLC22 genes identified in this study in relation to renal cell cancer and various oncologic variables (TNM class) used to determine pathologic stage, we note previous work has shown that SLC22A2, SLC22A12, and SLC22A13 are downregulated in human kidney tumors." (PMID 36230695, 2022).
breast carcinoma (2 papers, 2020 to 2021). "Similarly, a BA-deletion in the genome of a patient with breast adenocarcinoma correlated with 26-fold overexpression of SLC22A2 compared with the rest of the patients with breast cancer." (PMID 32024999, 2020). "SLC22A2, SLC22A16, and SLCO1A2 were not expressed in any of the investigated breast cancer cell lines (Ct values > 35)." (PMID 35008681, 2021).
chronic kidney disease (2 papers, 2019 to 2025). Impairment of the renal function secondary to chronic kidney damage persisting for three or more months. "In early studies, SLC22A2 expression was significantly lowered in adenine-induced chronic renal failure rats." (PMID 30239845, 2019). "This study revealed that bosutinib-induced elevation of serum creatinine, which was more pronounced in patients with the SLC22A2 808G/G genotype, does not indicate chronic kidney disease, but rather is simply a laboratory abnormality." (PMID 40000571, 2025).
esophageal cancer (2 papers, 2021 to 2025). A primary or metastatic malignant neoplasm involving the esophagus. "In addition, we could not validate the findings of the previously published candidate gene study on ERCC1 (rs11615 and rs3212986), ERCC2 (rs13181 and rs1799793), and SLC22A2 (rs316019) in our head and neck and esophageal cancer discovery cohort." (PMID 34834585, 2021).
Insulin resistance (2 papers, 2022 to 2025). Increased resistance towards insulin, that is, diminished effectiveness of insulin in reducing blood glucose levels. "Since the increased likelihood of developing T2DM is linked to insulin resistance, it is also worth discussing the potential effect of SLC22A2 on this condition." (PMID 40775340, 2025). "While the association between SLC22A2 genetic variations and insulin resistance remains an area of ongoing research, it is possible that these polymorphisms may significantly impact the effectiveness of metformin in managing T2DM." (PMID 40775340, 2025).
atherosclerosis (1 paper, 2024). A disease characterized by the build-up of fatty material and calcium deposition in the arterial wall resulting in partial or complete occlusion of the arterial lumen. "Altogether, these findings indicate that SLC22A2 may play a role in regulating serum lipid levels, thereby potentially influencing the risk of atherosclerosis and CAD." (PMID 39258111, 2024).
bladder cancer (1 paper, 2024). "Notably, the anticipated lower cytotoxicity of IMT is attributed to the observed lower expression levels of its primary targets, HIPK4 and SLC22A2, in bladder cancer compared to the targets of GCB and 5-FU." (PMID 38399266, 2024). "This projection stems from the observation that the primary targets for IMT (HIPK4 and SLC22A2) are not expressed as significantly in bladder cancer compared to the targets of GCB and 5-FU." (PMID 38399266, 2024).
clear cell renal carcinoma (1 paper, 2023). A malignant epithelial neoplasm of the kidney characterized by the presence of lipid-containing clear cells within a vascular network. "The OCT2/SLC22A2 protein and mRNA expression was found to be higher in clear cell renal carcinoma and lower in hepatocellular carcinoma as compared to non-cancerous tissues." (PMID 36839686, 2023).
deafness (1 paper, 2018). An inherited or acquired condition characterized by the complete loss of the ability to hear from one or both ears. "We did not include the SNPs in the following genes: ACYP2 (coding for an acylphosphatase), SLC31A1 gene coding for the copper transport protein 1, SLC22A2 coding for the organic cation transport protein 2, megalin, TPMT and COMT and Mendelian deafness gene." (PMID 30112115, 2018).
depressive disorder (1 paper, 2022). A melancholy feeling of sadness and despair. "Despite this lack of specific data on SLC22A2 variants on the risk of depressive disorders, gene-diseases association biobanks suggest they may have the second highest association strength (after SLC6A4)." (PMID 36557240, 2022).
hearing loss (1 paper, 2020). "Another candidate-gene study reported that the variant T allele of the solute carrier family 22 member 2 (SLC22A2) rs316019 was associated with hearing loss in 41 patients with HGOS." (PMID 32629971, 2020).
Hypertension (1 paper, 2024). The presence of chronic increased pressure in the systemic arterial system. "We also identified Translocase Of Outer Mitochondrial Membrane 40 (TOMM40) variants associated with CAD; Solute carrier family 22 member 2 (SLC22A2) variants associated with CAD and CVD; and HLA-DQA1 variants associated with hypertension." (PMID 39258111, 2024). "Our results place NOS3 gene as the common nexus between CAD, CVD and hypertension, with serum lipids connected to CVD through SLC22A2, in combination with TOMM40 for CAD and to hypertension through HLA-DQA1." (PMID 39258111, 2024). "TOMM40, one of the genes associated with CAD but not with CVD or the blood pressure related phenotypes (hypertension, SBP and DBP), was common for all the serum lipids, along with SLC22A2, which was common for CVD and all serum lipids." (PMID 39258111, 2024).
injury (1 paper, 2017). Damage inflicted on the body as the direct or indirect result of an external force, with or without disruption of structural continuity. "Based on our data and the supporting literature, variants in the SLC22A2 gene were related to risk or mitigation of risk for cisplatin induced kidney injury." (PMID 28640195, 2017).
liver cancer (1 paper, 2019). An epithelial or non-epithelial malignant neoplasm that arises from the liver. "Indeed, ALX3, GJD2, and SLC22A2, are linked to the IPA pathways 'liver carcinoma' and 'hepatobiliary system cancer'." (PMID 31695765, 2019).
renal papillary cell carcinoma (1 paper, 2020). "PDZK1, SLC22A2, and SLC44A4 have also a prognostic value for patients with renal papillary cell carcinoma." (PMID 32599841, 2020).
cancer (13 papers, 2012 to 2024). A tumor composed of atypical neoplastic, often pleomorphic cells that invade other tissues. "A SNP of OCT2 gene (SLC22A2), rs316019, was found to be associated with reduced nephrotoxicity from cisplatin in cancer patients." (PMID 24734245, 2014). "In addition, candidate genetic markers are useful for identifying childhood cancer patients at risk of severe late effects, such as SLC22A2, which detects those at risk of platinum-induced hearing loss." (PMID 37046624, 2023). "All of the four SLC transporters showed associations only with increased OS rates in cancers, including 1) SLC15A2 (LUAD), SLC22A1 (LIHC), SLC22A2 (KIRC, KIRP), and SLC22A6 (KIRC)." (PMID 33202946, 2020). "The 13 overexpressed genes were reported to play a role in RCC: PAX2, NAT8, GBA3, SLC22A2 other cancer types: AOC1, HAO2, TMEM27, cell death (NPR3) or kidney metabolism: TMEM171, CYS1." (PMID 31150395, 2019). "These authors subsequently evaluated changes to serum creatinine after treatment with cisplatin in human cancer patients (n = 78) according to the presence or absence of a copy of the nonsynonymous SLC22A2 rs316019 variant denoting reduced OCT2 function." (PMID 28640195, 2017). "In the case of G3 cancer, significant reduction in ARRB2 and DLG4 levels and overexpression of TERF2IP and SLC22A2 were observed." (PMID 34768458, 2021).
tumor (10 papers, 2011 to 2023). "In KIRC, the stratification of patient data by pathological tumor characteristics revealed the importance of SLC22A2, SLC22A6, and SLC22A12 in disease progression." (PMID 36230695, 2022). "While multiple comparisons had no DE genes in the entire expressed gene list (i.e., Stage III vs. Stage IV), there were 6 DE SLC22 genes in the Tumor Size and Progression comparison in KIRC [SLC22A2, SLC22A5, SLC22A6, SLC22A11, SLC22A12, SLC22A18] (T3 v T4)." (PMID 36230695, 2022). "We assessed tumor proliferation (Ki-67) and the expression of proteins involved in lipid metabolism and transport (CPT1, SLC22A2, SLC22A5, SLS25A20) by immunohistochemistry." (PMID 34356874, 2021). "DNA methylation of SLC22A2 in HCC and adjacent non-tumor liver tissue was high and showed low inter-individual variability." (PMID 22196450, 2011). "The under-expression of SLC22A1, SLC22A2, SLC47A1, CTR1, and CTR2 leads to reduce uptake of cisplatin whereas the upregulation of ATP7A, ATP7B, MRP1, MRP2, and MRP4 are responsible for increased efflux of cisplatin out of the tumor cell." (PMID 36715825, 2023). "DNA methylation, quantified by MALDI-TOF mass spectrometry and gene expression of SLC22A1, SLC22A2 and SLC22A3 were investigated using fresh-frozen HCC (n = 22) and non-tumor adjacent liver tissues as well as histologically normal liver samples (n = 120) from a large-scale liverbank." (PMID 22196450, 2011). "Moreover, specific antibodies were used to detect SLC22A1, SLC22A2 and SLC22A3 protein by immunofluoresence confocal laser scanning microscopy in HCC tumor tissue (n = 7 from HCC cohort 1) and histologically normal liver tissue (n = 5 from IKP-liverbank) derived from patients without HCC." (PMID 22196450, 2011). "Sixteen nearby genes showed higher expression in non-cancerous tissues, including seven with almost no expression in tumor (HCN1, SLC22A2, FAM3D, LRFN5, LINC01612, LINC02512, and CNBD1)." (PMID 37509325, 2023).
kidney disease (3 papers, 2021 to 2024). "Our results confirm previously identified associations of NEMG (NAT8, GATM, SLC22A2, WDR72, NOS3, AGXT2 and CPS1) with kidney disease and kidney function, providing new information that expands these associations to other kidney disease biomarkers." (PMID 38858654, 2024). "Interestingly, variants in the genes coding for SLC22A2 and SLC22A12 were related to susceptibility for kidney disease, and SLC22A2 polymorphisms are related to maintenance of kidney function after cisplatin exposure." (PMID 33618665, 2021).
psychiatric disorder (2 papers, 2016 to 2022). A disorder characterized by behavioral and/or psychological abnormalities, often accompanied by physical symptoms. "Combining the two variables, an opposite effect of SLC22A2 variants according to pre-existing psychiatric disorders was observed." (PMID 36557240, 2022). "We also reported here that the single nucleotide polymorphisms we studied (SLC22A2 808 C>A) was unevenly distributed among people living with HIV diagnosed with psychiatric disorders, suggesting a potential genetic/disease interaction." (PMID 36557240, 2022). "We confirm here that SLC22A2 CA/AA carriers had a significantly higher risk of psychiatric disorders and of being treated with antidepressants." (PMID 36557240, 2022). "The probability of discontinuing DTG according to SLC22A2 variants was different in participants without (higher in CA/AA carriers) and with (lower in CA/AA carriers) pre-existing psychiatric disorders." (PMID 36557240, 2022). "Instead, other groups have previously demonstrated an involvement of Slc22a2 or Htr4 in the efficacy of antidepressant medication, whereas Gabrg2 holds high relevance seen the involvement of GABAergic transmission in several psychiatric disorders." (PMID 27824361, 2016).
SLC22A2 also shares sentences with these, for which no sentence is quoted: type 2 diabetes mellitus (5 papers); Primary carnitine deficiency (3); colorectal cancer (2); Hypomagnesemia (2); acute kidney injury (1); Alzheimer disease (1); Anxiety (1); brain tumor (1); breast adenocarcinoma (1); cardiomyopathy (1); Carnitine palmitoyltransferase deficiency type 2 (1); chronic myeloid leukemia (1); colon carcinoma (1); cyst (1); head and neck cancer (1); heart failure (1); Hyperglycemia (1); Hypoalbuminemia (1); kidney damage (1); kidney tumors (1); lactic acidosis (1); medulloblastoma (1); mucopolysaccharidosis type 1 (1); non-small cell lung carcinoma (1); Obesity (1); ovarian carcinoma (1); peripheral neuropathy (1); peripheral neurotoxicity (1); renal carcinoma (1); renal dysfunction (1).
A further 6 diseases each share a sentence with SLC22A2 in 1 paper.